FGF23 (fibroblast growth factor 23)
Diseases named in the same sentence as FGF23 in open-access papers (continued):
Sharing a sentence is not in itself a finding about the gene and the disease.
diabetes (continued). "Model 2, with age, sex, and eGFR, had a larger AIC (2,350.1) compared to that for model 7 (model 1 plus SBP, diabetes, log-UACR, serum albumin, and Hb) and model 9 (model 7 plus log-iPTH and log-FGF-23), which had AICs of 2,216.3 and 2,211.6, respectively." (PMID 30069609, 2019). "Furthermore, high FGF23 levels were also significantly associated with the future development of anemia in patients with low disease severity (e.g., with well-controlled BP, no diabetes, no obesity, and low comorbid conditions)." (PMID 29740119, 2018). "Following adjustment for the total study population, only diabetes, higher baseline PWV and higher FGF23 remained independent predictors of PWV at 12 months." (PMID 28870151, 2017). "Cases were more likely to live in the US stroke belt, have lower income, have diabetes, CHD, and CKD, be current smokers, and have lower 25(OH)D concentrations and higher FGF23 concentrations than controls." (PMID 27812184, 2016). "Multivariable analysis demonstrated a significant negative relationship between CAC SRVT and peak LV systolic velocity after adjustment for age, diabetes status, gender, CAD status, and FGF-23 level (Std." (PMID 27805564, 2016). "Patients with both type 1 and type 2 diabetes are more likely to display deregulations in bone and mineral metabolism including elevated FGF23 levels, compared to individuals without diabetes." (PMID 40237064, 2025). "Independent predictors of high cDPP3 included liver enzymes (alanine aminotransferase, bilirubin), the absence of diabetes, and elevated osteopontin, fibroblast growth factor-23 (FGF-23), and NT-proBNP, all with p < 0.001." (PMID 41226854, 2025). "Notably, combined diabetes mellitus and hypertension demonstrated substantial differences in results when changing the effect model, while age, hypertension, SOST, and FGF-23 showed consistent results across both models." (PMID 40314886, 2025). "In KTRs without diabetes at baseline, the highest tertile of FGF23, compared to the lowest, is predictive for development of PTDM." (PMID 38577264, 2024). "This study aimed to investigate the relationship between bone metabolism markers, including serum klotho, fibroblast growth factor 23 (FGF23), 25(OH)D3, iPTH, calcium (Ca), and PHOS and the progression of diabetic kidney disease (DKD) in patients with type 2 diabetes mellitus (T2DM)." (PMID 39558979, 2024). "In patients with CKD and diabetics, serum levels of MMP-2, MMP-8, and MMP-9 were found to be higher, being correlated with serum phosphate (MMP-2), fibroblast growth factor-23 (FGF-23), and proteinuria (MMP-8 and MMP-9), which are both associated with oxidative stress and cardiovascular health." (PMID 37840653, 2023). "A large cohort of 3,115 elderly subjects with diabetes demonstrated that FGF23 levels were not related to the IR." (PMID 35966090, 2022). "Applying different prediction models, the authors found that baseline FGF23 does not predict the incidence of CKD in patients with diabetes, although they suggested the contribution of this parameter to CKD progression, once already established." (PMID 33673618, 2021). "Finally, several clinical studies have linked the baseline characteristics of individuals with high plasma levels of FGF-23, discovering a direct correlation with bad health habits, MBD and CKD and with comorbidities such as diabetes and hypertension." (PMID 33767635, 2021). "After matching, FGF23 levels remained higher in patients with type 2 diabetes than in patients without diabetes (75.6 [IQR 61.3–91.8] vs. 70.8 [IQR 58.0–85.8] RU/mL, respectively, P < 0.001)." (PMID 32857288, 2020). "The current literature indicates that patients with type 2 diabetes, and particularly those with impaired kidney function, generally have an increased FGF23 level compared with individuals without diabetes." (PMID 32857288, 2020).
diabetes (continued). "The presence of diabetes mellitus, FGF23 levels, and existing residual renal function were not significant predictors for 3-year all-cause and CV mortality in MHD patients in our study." (PMID 30977017, 2019). "The lowest (best) AIC presented in the model 10 came from the forward selection stepwise method (model 8 without diabetes plus hypertension, serum calcium, serum phosphorus, and log-FGF-23)." (PMID 30069609, 2019). "A small study of subjects with diabetes and impaired renal function at baseline reported that FGF-23 was a predictor of renal outcome independent of creatinine clearance, although its 12 ESRD events did not allow a fully adjusted Cox analysis." (PMID 23526964, 2013). "Together, these studies suggest that insulin and glucose have opposed effects on FGF23 levels, but these effects may also be context-dependent, as insulin clamping did not lead to increased FGF23 levels in individuals without diabetes." (PMID 40237064, 2025). "In this cohort of KTRs, individuals in the highest tertile of plasma FGF23 during the first 24 months post transplant had a higher risk of developing PTDM compared to those in the lowest tertile, independent of diabetes-related or transplant-related risk factors." (PMID 38577264, 2024). "It is not known whether the higher levels of FGF23 found in patients with diabetes and CKD may contribute to the worse clinical outcomes observed in these patients compared to subjects with CKD without DM." (PMID 38791495, 2024). "This study aimed to determine whether FGF23 may be used as a marker of myocardial damage among patients with diabetes mellitus type 2 (T2DM) and no previous history of myocardial infarction." (PMID 37371618, 2023). "In addition, many factors are reported to affect serum FGF23 levels in patients with diabetes, including—but not limited to—serum phosphate, inflammation, early tubular injury, insulin, and oral glucose loading." (PMID 36084108, 2022). "It was suggested that CHD is closely related to smoking, hypertension, diabetes, alcohol consumption, obesity, HDL-C, FGF23, SAH, Hcy and HOMER1, and FGF23, SAH, Hcy and HOMER1 are new risk factors for CHD, which may have an important reference value for the clinical diagnosis of CHD." (PMID 35546659, 2022). "Diabetes medications appeared not to be related to the FGF23 level as well." (PMID 35736431, 2022). "The relationship between altered mineral metabolism components, including FGF23/α-klotho, and atherosclerosis in subjects with type 1 diabetes mellitus (T1D) without previous cardiovascular events and kidney impairment is supported by different lines of evidence." (PMID 36221075, 2022). "Moreover, FGF23 excess was more prevalent earlier in the course of CKD among those with diabetes versus those without diabetes [14••]." (PMID 32857288, 2020). "Initial studies were already suggestive of deregulated FGF23 levels in diabetes, compared with non-diabetic controls, but the limited sample size and heterogeneity of these studies could have confounded the results." (PMID 32857288, 2020). "While the conditions that determine FGF23 levels in patients with diabetes and preserved kidney function are not entirely clear, there seems to be interaction between diabetes and kidney function, with the highest FGF23 levels present in patients with both diabetes and impaired kidney function." (PMID 32857288, 2020). "However, other variables, including the gender (male), presence of diabetes mellitus, urine volume ≥ 100 ml/day, average ultrafiltration, serum potassium, phosphate, iPTH, and Log FGF23, were not." (PMID 30977017, 2019). "In a mixed diabetic and non-diabetic cohort of patients with coronary heart disease, higher FGF-23 predicted CV outcomes in the diabetic but not in the non-diabetic patients suggesting potential biological differences in the FGF-23 response between patients with and without diabetes." (PMID 29698460, 2018).
diabetes (continued). "Hence, color Doppler ultrasound imaging was used to detect abnormalities in the lower extremity arteries in the present study, in order to investigate the relationship between serum FGF23 levels and LEAD, as well as the related factors, in Chinese patients with type 2 diabetes mellitus (T2DM)." (PMID 28619026, 2017). "Notably, the relationship between the presence of diabetes and altered serum FGF23 levels was reported to be independent of cardiovascular risk factors in previous studies." (PMID 27698482, 2016). "The present study revealed a significant increase in serum FGF23 levels in normoglycemic individuals with a first-degree FHD, accompanied by increases in serum insulin levels and HOMA-IR values, and these findings are consistent with those of most studies of diabetes populations." (PMID 27698482, 2016). "Vitamin D and FGF23-Klotho signaling pathways have provided important insight into the scientific basis of the TCM theory “Kidneys Govern Bones” and have helped us understand how vascular complications and metabolic bone disorder evolve in CKD and diabetes mellitus." (PMID 27668003, 2016). "In addition, the role played by FGF-23 in phosphate regulation and bone metabolism is likely different in diabetes mellitus patients from those without diabetes mellitus." (PMID 26186634, 2015). "While cross-sectional studies reviewed above strongly suggest a relationship between FGF23 levels and (deregulated) glucose homeostasis, they do not clarify whether the development of insulin resistance or diabetes drives abnormal mineral homeostasis, the opposite, or both." (PMID 40237064, 2025). "Using IVW, genetically predicted higher FGF23 was inversely associated with risk of CAD [odds ratio (OR): 0.69 per logtransformed FGF23 (pg/ml) increase, 95% confidence interval (CI): 0.52–0.91] and type 2 diabetes mellitus (T2DM) (OR: 0.70, 95% CI: 0.52–0.96), but not with the other outcomes." (PMID 34367258, 2021). "Although vascular calcification is a prominent feature of cardiovascular disease in diabetes, particularly with co-existing CKD, it does not seem to be the only pathway linking FGF23 with adverse outcomes." (PMID 32857288, 2020). "In conclusion, this study for the first time demonstrates that Cholecalciferol improves endothelial vasomotor and secretory function, in stable non-diabetes stage 3/4 CKD patients without any significant effect on arterial stiffness, calcium and FGF-23 levels." (PMID 24646518, 2014). "Moreover, a correlation between serum FGF23 levels and carotid IMT has been reported previously by our study team in a Chinese population without diabetes, even in individuals with normal glucose tolerance." (PMID 28619026, 2017).
iron deficiency (127 papers, 2012 to 2026). "Through a number of interrelated mechanisms, including iron deficiency, iron overload, oxidative stress, FGF23-mediated mineral disturbances, and compromised muscle function, iron dysregulation leads to bone fragility." (PMID 41496457, 2026). "Since iron deficiency stimulates both FGF23 expression and cleavage, hepcidin-mediated functional iron insufficiency influences the FGF23 levels in a similar fashion." (PMID 40142640, 2025). "Normally, iron deficiency increases FGF23 transcription but enhances its proteolytic cleavage, resulting in low levels of intact hormone." (PMID 41235284, 2025). "The use of burosumab has also been reported in FGF23-mediated hypophosphatemic osteomalacia secondary to repeated intravenous iron infusions in a 32-yr-old man with severe Crohn’s disease and iron-deficiency anemia." (PMID 41445556, 2025). "Iron deficiency upregulates hepcidin and hypoxia-inducible factor 1α (HIF1α), regulating, and promoting the transcription of fibroblast growth factor 23 (FGF-23), a hormone derived from osteocytes, regulating phosphate, and vitamin D homeostasis." (PMID 41445550, 2025). "These fragments are even stronger predictors of mortality than intact FGF23, reflecting the true burden of the underlying iron deficiency, inflammation, and disease progression." (PMID 41515987, 2025). "Factors that have been reported to concurrently increase FGF23 transcription and post-translational cleavage, resulting in the disproportionate cellular secretion of FGF23 fragments, include iron deficiency, erythropoietin, and inflammation." (PMID 37752381, 2024). "Previous studies have suggested that iron deficiency can impair renal phosphate reabsorption due to alterations in fibroblast growth factor-23 (FGF23) levels, a key regulator of phosphate homeostasis." (PMID 39850154, 2024). "When these phosphaturic preparations are administered in the situation of iron deficiency with increased FGF23 transcription, they would inhibit the FGF23 cleavage process leading to an increase in iFGF23." (PMID 38732094, 2024). "This iron deficiency, either absolute or relative, has been associated with increased levels of the active form of FGF23 (iFGF23) in animal models with CKD." (PMID 38732094, 2024). "It has been suggested that increased inflammation and iron deficiency play a role through alteration of FGF23 transcription and post-translational modification." (PMID 38770543, 2024). "Work from our lab demonstrated that increased FGF23 is a causative factor in the development of anemia, iron deficiency, and inflammation in mice with renal failure but also in mice with normal kidney function." (PMID 39666728, 2024). "To date, the literature agrees that inflammation, anemia, and iron deficiency contribute to higher FGF23 levels, but it is still unclear if and which specific biomarker(s) is(are) associated with the synthesis and/or cleavage of this hormone." (PMID 38999530, 2024). "Feedback systems have been described between Epo and FGF-23—which is also produced in the bone marrow through the stimulation from Epo itself—similar to conditions of inflammation and iron deficiency." (PMID 39684548, 2024). "Female ADHR patients show hypophosphatemic flares coinciding with menses and pregnancy, conditions associated with iron deficiency, suggesting increased FGF-23 production." (PMID 39684548, 2024). "Iron deficiency is a risk factor for cardiovascular events and mortality, and higher levels of fibroblast growth factor 23 (FGF23) are associated with increased risks of each." (PMID 38402503, 2024). "Fe is involved in bone formation, iron deficiency and iron-deficiency anemia are linked to phosphate metabolism, and FGF-23 transcription is elevated in iron deficiency." (PMID 39121099, 2024).
iron deficiency (continued). "Recent studies suggest that systemic inflammation and iron deficiency upregulate FGF23 transcription and cleavage into C-terminal FGF23, leading to a mild increase in iFGF23 but a significant increase in cFGF23." (PMID 38770543, 2024). "Iron deficiency stimulates production and increases proteolytic cleavage of FGF23, resulting in increases in circulating concentrations of C-terminal cleavage fragments." (PMID 38402503, 2024). "Numerous investigations provide evidence supporting the role of elevated FGF-23 as a causative factor in the initiation of renal anemia, chronic inflammation, and iron deficiency in the context of CKD." (PMID 39911241, 2024). "This suggests that the underlying biological processes that upregulate the production and cleavage of FGF23 or, the C-terminal fragments, are responsible for the detrimental cardiovascular effects of iron deficiency." (PMID 38375423, 2024). "Recent research revealed an important bidirectional crosstalk between FGF23, known as a major regulator of phosphate homeostasis, with iron deficiency and EPO production." (PMID 36831276, 2023). "A study with mice demonstrated an increase in FGF-23 production when absolute and functional iron deficiency was present." (PMID 37893926, 2023). "Impairment of osteocyte function and aberrant FGF23 production should also be emphasized in iron deficiency, another spectrum of iron dyshomeostasis." (PMID 38040893, 2023). "This is true even when there is concurrent iron deficiency or inflammation, factors that usually increase FGF23 cleavage and are highly prevalent in CKD." (PMID 37681408, 2023). "Iron deficiency state can increase FGF23 concentration and therefore in FGF23-related hypophosphatemic rickets, it can significantly worsen hypophosphatemic rickets." (PMID 37074534, 2023). "In an in vitro study, FGF23 mRNA expression in osteocyte-like cells was increased in iron deficiency conditions, and improvement of tissue iron utilization can reduce transcription and production levels of FGF238." (PMID 36823243, 2023). "Under conditions of iron deficiency, the transcription of fibroblast growth factor 23 (FGF-23) is increased." (PMID 37521459, 2023). "In fact, iron deficiency is associated with higher FGF23 levels in women with a history of heavy uterine bleeding and in patients undergoing HD." (PMID 37081846, 2023). "FGF-23 production and cleavage are influenced by not only phosphate levels, but also by iron deficiency, chronic inflammation, and EPO11." (PMID 36823243, 2023). "The induction of HIF1α in osteoblasts and osteocytes, in response to iron deficiency or hypoxia, increases FGF23 production." (PMID 36895836, 2023). "FGF23 cleavage is increased during iron deficiency and inflammation and in myelodysplastic syndrome." (PMID 37681408, 2023). "In a CKD mouse model, FGF23 signaling inhibition improved anemia and iron deficiency by increasing EPO levels, hemoglobin, red blood cells, bone marrow erythroid progenitors, and driving hematopoietic stem cells to the erythroid lineage." (PMID 36831276, 2023). "This suggested that iron deficiency leads to increased FGF23 expression, but increased cleavage retains homeostasis in humans without ADHR." (PMID 37808399, 2023). "Further, osteocytes directly controlled HIF-dependent FGF23 production via interactions with holo-transferrin during mimicked iron deficiency." (PMID 36650133, 2023). "Multiple factors stimulate FGF23 production, including dietary phosphate absorption and iron deficiency." (PMID 35237863, 2022). "Iron deficiency also concurrently increases intracellular FGF23 post-translational proteolytic cleavage, resulting in secretion of FGF23 protein fragments from the cell." (PMID 35237863, 2022). "In search for treatment options with less adverse effects, we previously reported that inhibition of FGF23 signaling by the use of an FGF23 antagonist successfully rescues renal anemia and attenuates iron deficiency and inflammation in a CKD mouse model." (PMID 35813388, 2022).